Y_RNA (Y RNA )
Gene: Miscellaneous RNA gene on chromosome 9 (93,417,855 to 93,417,966, forward strand). Ensembl gene ENSG00000201074.
Homologues: Orthologues: macaque Y_RNA (96% identical). Paralogues in human: RNY1 (89% identical), Y_RNA (87% identical), Y_RNA (85% identical), Y_RNA (84% identical), Y_RNA (83% identical), RNY1P11 (82% identical), Y_RNA (82% identical), RNY1P8 (81% identical), Y_RNA (81% identical), Y_RNA (80% identical), RNY1P7 (79% identical), Y_RNA (79% identical), and 97 more.